SNX25 (sorting nexin 25)
Description:
May be involved in several stages of intracellular trafficking.
Synonyms: MSTP043; SBBI31; LRP2BP-AS1
Tractability: Small molecule: a structure with a bound ligand is known. Antibody: UniProt places it where antibodies can reach, with high confidence. PROTAC: ubiquitination databases record sites on it; its protein half-life has been measured.
Gene: Protein-coding gene on chromosome 4 (185,204,237 to 185,390,928, forward strand). Ensembl gene ENSG00000109762.
Subcellular location: Endosome membrane
Subcellular location (Human Protein Atlas): Vesicles
Gene Ontology:
Molecular function: phosphatidylinositol binding
Biological process: negative regulation of transforming growth factor beta receptor signaling pathway; receptor catabolic process
Cellular component: endosome; endosome membrane
Genetic constraint (gnomAD): Loss-of-function variants: 52 observed, 97.58 expected, observed/expected ratio (o/e) 0.53, 90% interval 0.43 to 0.67. The upper end of that interval is the gene's LOEUF score, 0.67, which puts it in group 2 of 6, group 1 being the genes least tolerant of losing a copy. Missense variants: 958 observed, 1,147.8 expected, observed/expected ratio (o/e) 0.83, 90% interval 0.79 to 0.88. Synonymous variants: 398 observed, 446.42 expected, observed/expected ratio (o/e) 0.89, 90% interval 0.82 to 0.97.
Homologues: Orthologues: dog SNX25 (85% identical), macaque SNX25 (84% identical), chimpanzee SNX25 (83% identical), rat Snx25 (83% identical), guinea pig SNX25 (81% identical), rabbit SNX25 (79% identical), mouse Snx25 (73% identical), tropical clawed frog snx25 (69% identical), zebrafish snx25 (65% identical), pig SNX25 (57% identical), Drosophila melanogaster snz (13% identical). Paralogues in human: SNX13 (22% identical), SNX14 (16% identical), SNX19 (16% identical).
Diseases named in the same sentence as SNX25 in open-access papers:
SNX25 is named in the same sentence as 13 diseases in open-access papers, as found by Europe PMC text mining. Sharing a sentence is not in itself a finding about the gene and the disease. The quoted sentences say what the papers report.
allergic disease (2 papers, 2021 to 2022). An immune response that occurs following re-exposure to an innocuous antigen, and that requires the presence of existing antibodies against that antigen. "In particular, the hypermethylation of the gene encoding sorting nexin 25 (SNX25) is interesting in relation to allergic disease." (PMID 33668787, 2021). "The relationship between the hypermethylation of sorting nexin 25 (SNX25) gene and allergic disease is exciting." (PMID 35740242, 2022).
epilepsy (2 papers, 2015 to 2021). A brain disorder characterized by episodes of abnormally increased neuronal discharge resulting in transient episodes of sensory or motor neurological dysfunction, or psychic dysfunction. "Furthermore, SNX25 recent ascribed role in TrkB degradation and BDNF-TrkB signaling suggests additional associations with epilepsy and also with schizophrenia, attending on BDNF and TrkB-signaling molecules on the pathophysiology of these conditions." (PMID 33931804, 2021). "Still, much remains unknown about SNX25-dependent protein cargoes and its brain-expression and regulation, highlighting that SNX25 role in epilepsy may result from additional molecular pathway dysregulation." (PMID 33931804, 2021). "SNX25, another PXA-RGS SNX, is highly expressed in the temporal lobe of patients with epilepsy." (PMID 33931804, 2021).
Hypertension (1 paper, 2021). The presence of chronic increased pressure in the systemic arterial system. "Therefore, the SNX25 gene encoding protein SNX25 might be associated with hypertension, a risk factor for kidney disease." (PMID 34946851, 2021).
liver cancer (1 paper, 2026). An epithelial or non-epithelial malignant neoplasm that arises from the liver. "Circular SNX25 encodes a protein that enhances DNA damage repair, conferring radioresistance in liver cancer." (PMID 41487280, 2026).
neoplasm (1 paper, 2024). A benign or malignant tissue growth resulting from uncontrolled cell proliferation. "All but one of these genes was also identified in selection scans, and two of them were identified in all three transects: Snx25, which is linked to activity, cardiac function, and more recently, circadian pace-making and Ralgapa2, which is linked to neoplasm and glucose homeostasis." (PMID 38968323, 2024).
SNX25 also shares sentences with these, for which no sentence is quoted: amyotrophic lateral sclerosis (1 paper); Crohn disease (1); infection (1); inflammatory bowel disease (1); kidney disease (1); myelofibrosis (1); prostate carcinoma (1); type 2 diabetes (1).